PAPPA (pappalysin 1)
Diseases named in the same sentence as PAPPA in open-access papers (continued):
Sharing a sentence is not in itself a finding about the gene and the disease.
lung carcinoma (18 papers, 2012 to 2026). "PAPPA is implicated in breast, ovarian, and lung cancers, as well as Ewing sarcoma, making it a potential therapeutic target." (PMID 41583513, 2026). "LIF and PAPPA, whose expression levels were associated with worse survival of lung cancer patients, were down-regulated in lung cancer H1299 cells after transfection of miR-500a-3p compared to control miRNA mimetic by qRT-PCR." (PMID 28952053, 2018). "In contrast, miR-500a-3p was significantly associated with longer survival of lung cancer patients and targeted two cancer-associated genes, LIF (leukemia inhibitory factor) and PAPPA (pregnancy-associated plasma protein A, pappalysin 1)." (PMID 28952053, 2018). "Over-expression of PAPPA in two different lung cancer cells, H1299 and H1792 at similar protein level, however, resulted in different outcomes." (PMID 23152806, 2012). "In this study we found that PAPPA is secreted from two out of seven lung cancer cell lines examined." (PMID 23152806, 2012). "Here we report that ectopic over-expression of PAPPA in H1299 lung cancer cells promotes tumor growth in vivo in a xenograft model while down regulation of endogenous PAPPA in A549 lung cancer cells decreases tumor growth." (PMID 23152806, 2012). "In the view of the controversial roles of PAPPA reported in cancer development, we decided to over-express PAPPA in lung cancer cell lines to evaluate its role on tumor growth and progression." (PMID 23152806, 2012). "Taken together, these results indicate PAPPA secreted from tumor cells plays an essential role in promotion of lung cancer cell proliferation and progression in vivo." (PMID 23152806, 2012). "Together these results suggest that LIF and PAPPA may be biological targets of miR-500a-3p in lung cancer cells." (PMID 28952053, 2018). "Our data reveal LIF and PAPPA as potential targets of miR-500a-3p in lung cancer cells." (PMID 28952053, 2018). "PAPPA has been shown to promote lung cancer growth and progression." (PMID 28952053, 2018). "In addition, serum PAPPA level has been reported to be increased in patients with lung cancer in comparison with healthy subjects." (PMID 23152806, 2012). "Our results indicate that expression of PAPPA in lung cancer cell lines varies greatly." (PMID 23152806, 2012). "Our results indicate that PAPPA secretion may play an important role in lung cancer growth and progression." (PMID 23152806, 2012). "We first tested the hypothesis whether the increased plasma concentration of PAPPA observed in lung cancer patients is due to secretion of PAPPA directly from lung cancer cells." (PMID 23152806, 2012). "Thus the secreted form of PAPPA from cancer cells may contribute to the growth and progression of some types of lung cancer." (PMID 23152806, 2012). "Interestingly, studies in ovarian, breast and lung cancer as well as malignant pleural mesothelioma revealed the cancer rather than the stromal cells as the cellular source of PAPPA." (PMID 26020769, 2015).
Obesity (15 papers, 2009 to 2025). Accumulation of substantial excess body fat. "The hypothesis of the study is that PAPPA could be a clinical marker of obesity in the third trimester independent of diet in uncomplicated pregnancies." (PMID 39585163, 2024). "Notably, in men with obesity and DM2, the genes up-regulated due to bright light include fibroblast growth factor 1 (FGF1), vasorin (VASN), ribonuclease A family member 1 (RNASE1), pappalysin 1 (PAPPA), Interleukin 7 (IL7), and fatty acid binding protein 3 (FABP3)." (PMID 40981208, 2025).
Ewing sarcoma (7 papers, 2017 to 2026). A small round cell tumor that lacks morphologic, immunohistochemical, and electron microscopic evidence of neuroectodermal differentiation. "An RNA-seq study in Ewing sarcoma cell lines with PAPPA knockout demonstrated the induction of immune related genes and the downregulation of reactive oxygen species, DNA repair and the endoplasmic reticulum unfolded protein response." (PMID 38395880, 2024). "Silencing of pappalysin-1 strongly inhibited anchorage-dependent and anchorage-independent growth as well as xenograft tumorigenicity of Ewing sarcoma cells." (PMID 29321818, 2017). "Pappalysin-1 silencing strongly inhibited both anchorage- dependent and anchorage-independent growth as well as xenograft tumorigenicity of Ewing sarcoma cells." (PMID 29321818, 2017). "Among these, PAPPA was discovered to be a highly differentially expressed therapeutic target in Ewing sarcoma, COL8A2 is a crucial part of the basement membrane of corneal endothelial cells, and it can encourage the malignant development of glioblastoma cells by triggering EMT." (PMID 37777759, 2023). "Silencing of pappalysin-1 resulted in accumulation of IGFBPs and reduced bioactive IGF-1 in Ewing sarcoma cell secretome, leading to suppression of IGF signaling." (PMID 29321818, 2017).
Insulin resistance (7 papers, 2017 to 2025). Increased resistance towards insulin, that is, diminished effectiveness of insulin in reducing blood glucose levels. "PAPPA-deficient mice develop insulin resistance in pregnancy." (PMID 35059395, 2021).
gastric cancer (5 papers, 2012 to 2026). A primary or metastatic malignant neoplasm involving the stomach. "High PAPPA expression was associated with poorer overall survival in bladder, cervical, lung squamous, mesothelioma, pancreatic, and gastric cancers, but exhibited a protective effect in lower-grade glioma." (PMID 41892220, 2026).
prostate carcinoma (5 papers, 2017 to 2025). A carcinoma that arises from epithelial cells of the prostate gland. "Circular RNA pappalysin-1 (circ-PAPPA) is a circRNA discovered to be up-regulated in prostate cancer and it can promote prostate cancer progression." (PMID 39951875, 2025). "In prostate cancer, by sequestering miR-515-5p, Circ-PAPPA enhanced malignant phenotypes of prostate cancer cells by enhancing the expression of FKBP1A." (PMID 36499275, 2022). "In silico analysis to map the function of these secreted factors identified PAPPA, IGFBP2, DKK1, and TGFβ1, which have documented effects on “invasion of tumor cells” or “prostate cancer and tumors”." (PMID 29088840, 2017).
thyroid cancer (5 papers, 2017 to 2026). "We first demonstrated that PAPPA behaves as a promising diagnostic marker for differentiated thyroid cancer contributing to the pre-surgical classification of thyroid nodules according to the final histology." (PMID 35563038, 2022). "PAPPA was reduced in several cancers and primarily localized to stromal cells, whereas in cholangiocarcinoma and thyroid carcinoma it was elevated and also detected in malignant cells." (PMID 41892220, 2026). "PAPPA mRNA expression measured by qRT-PCR was significantly higher (p < 0.0001) in 64 thyroid cancers compared to their benign counterparts." (PMID 34350538, 2022). "We found that PAPPA expression was increased in thyroid cancer specimen at mRNA and protein levels and that, adenomas and hyperplastic nodules had an expression similar to normal tissues." (PMID 34350538, 2022). "Pregnancy-associated plasma protein A (PAPPA) acts as an oncogene, and its expression is increased in multiple malignancies, including thyroid cancer." (PMID 35563038, 2022). "In literature, data are missing about the relationship between PAPPA and thyroid cancer, although the IGF axis has been actively investigated in thyroid tumorigenesis." (PMID 34350538, 2022). "In this report, we have shown that PAPPA mRNA expression is increased in thyroid cancer compared to benign lesions in surgical specimen." (PMID 34350538, 2022). "PAPPA mRNA expression was higher in thyroid cancer compared to hyperplastic nodules and adenomas (p < 0.001) and this difference was more evident when we group the benign pathologies and compared the results with cancer (p < 0.0001)." (PMID 34350538, 2022). "This is the first report showing elevated PAPPA mRNA expression in a robust series of thyroid cancer specimen (n = 64) comparing with normal thyroid counterparts and benign thyroid lesions (14 hyperplastic nodules and 16 adenomas)." (PMID 34350538, 2022). "Molecules like PAPPA, TIMP1, and HMGA2 are particularly noteworthy due to their substantial sample sizes and diagnostic utility, making them promising candidates for enhancing thyroid cancer diagnosis." (PMID 40346322, 2025). "In addition to pregnancy, PAPPA was found to be increased in several tumors, including thyroid cancer." (PMID 35563038, 2022). "So, further explorations will occur to deep the mechanism(s) by which PAPPA might contribute to the pathogenesis of thyroid cancer." (PMID 34350538, 2022). "In our study, we aimed to characterize the expression levels of PAPPA and other components of the IGF system in a wider number of thyroid cancer specimen and compare the results with mRNA levels in adjacent healthy tissues as well as in hyperplastic nodules and adenomas." (PMID 34350538, 2022). "However, authors have analyzed PAPPA levels in a small number of thyroid cancers (n = 26) and compared to only 4 non-tumor tissues." (PMID 34350538, 2022).
breast tumors (4 papers, 2020 to 2022).
Infertility (4 papers, 2019 to 2025). "A limitation of our study was lack of information on the causes of infertility, number and kind of embryos, freeze or fresh embryo transfer; also, we did not evaluate its correlation with biomarker levels such as PAPPA and free β-hCG." (PMID 31037917, 2019).
invasive breast carcinoma (4 papers, 2017 to 2022). A carcinoma that infiltrates the breast parenchyma. "Previous studies implicated PAPPA in the progression of precancerous breast nodule and invasive breast cancer." (PMID 34974815, 2022).
ovarian tumor (4 papers, 2012 to 2021). "The PAPPA gene is located in a chromosomal region associated with high frequency of loss of heterozygosity in ovarian tumors." (PMID 32982990, 2020). "PAPPA gene is localized in a chromosomal region associated with high frequency of loss of heterozygosity in ovarian tumors." (PMID 23152806, 2012).
Cognitive impairment (3 papers, 2017 to 2024). Abnormal cognition is characterized by deficits in thinking, reasoning, or remembering. "Likewise, plasma concentrations of myostatin, PI3, TFF3, and PAPPA have been shown to identify at-risk individuals with high accuracy and well before clinical signs of cognitive impairment appear." (PMID 38337499, 2024).
hepatocellular carcinoma (3 papers, 2015 to 2024). A malignant tumor that arises from hepatocytes. "Among the cabozantinib-induced secreted factors, PAPPA was previously shown to be a stroma-secreted factor that can activate NFκB signaling in hepatocellular carcinoma (HCC) cells, and advanced stage HCC has higher expression levels of PAPPA." (PMID 29088840, 2017).
hyperandrogenemia (3 papers, 2009 to 2024). "There was a difference when stratifying according to hyperandrogenemia, with APCS, ApoE and ApoA1 higher in hyperandrogenemia (p < 0.01, p < 0.04 and p < 0.01, respectively), while PAPPA was decreased in hyperandrogenemia (p < 0.01)." (PMID 38256230, 2024). "When stratified according to demographic parameters, hyperandrogenemia showed increased APCS, ApoE and ApoA1, whereas PAPPA was decreased." (PMID 38256230, 2024).
metastatic disease (3 papers, 2015 to 2020). "We also examined expression of PAPPA in 47 melanoma patient tumor samples and detected PAPPA expression in 87% of metastatic tumors tested." (PMID 25940796, 2015).
Pleural effusion (3 papers, 2013 to 2024). The presence of an excessive amount of fluid in the pleural cavity. "In addition, NCI-H290 cells transfected with PAPPA shRNA, when inoculated into the pleural cavity of SCID mice, failed to develop tumors in vivo, while NCI-H290 transfected with control shRNA developed massive tumors and bloody pleural effusions." (PMID 23896451, 2013). "On the other hand, PAPPA shRNA NCI-H290 only developed traces of tumor mass, and almost no pleural effusions were observed." (PMID 23896451, 2013). "Furthermore, PAPPA shRNA transfected NCI-H290 when orthotopically inoculated into pleural cavity of severe combined immunodeficiency recipient mice, failed to develop tumors and produce bloody pleural effusion as control shRNA transfected cells did." (PMID 23896451, 2013).
cyst (2 papers, 2021 to 2025). A sac-like closed membranous structure that may be empty or contain fluid or amorphous material. "The cyst-derived stromal cells exhibited early chromosomal instability and overexpression of MMP1 and PAPPA, supporting their potential role in ovarian carcinogenesis." (PMID 41296178, 2025). "Transcriptomic profiling further identified upregulation of MMP1, PAPPA, and CXCL chemokines in cyst-derived stromal cells, implicating extracellular matrix remodeling, IGF signaling, and inflammatory crosstalk as potential stromal drivers of ovarian carcinogenesis." (PMID 41296178, 2025).
endometrial cancer (2 papers, 2023 to 2025). Primary or metastatic malignant neoplasm involving the endometrium (mucous membrane that lines the endometrial cavity). "Additionally, several researchers have determined that in endometrial cancer, the YTHDF1 enhances the growth of tumors by controlling the ERK/NF‐κB/AKT signaling cascade via the PAPPA/IGFBP4 axis." (PMID 39821576, 2025).
melanoma (2 papers, 2015 to 2020). A malignant, usually aggressive tumor composed of atypical, neoplastic melanocytes. "Taken together, these data support a role for PAPPA in melanoma progression, particularly in association with high levels of PAPPA protein in pregnancy." (PMID 25940796, 2015). "We recently identified pregnancy-associated plasma protein-A (PAPPA) as a candidate gene with enriched expression in melanoma cells with a label-retaining phenotype." (PMID 25940796, 2015). "In this study, we establish a clear relationship between a pregnancy-associated protein PAPPA, melanoma and functional effects mediated through IGF1 that provides a plausible mechanism for accelerated melanoma progression during pregnancy." (PMID 25940796, 2015). "The silencing of PAPPA in both cell lines was associated with significantly reduced cell invasion and antibody treatment with anti-PAPPA antibody decreased the invasive ability of melanoma cells similarly." (PMID 25940796, 2015). "PAPPA protein expression patterns in melanoma tumors were determined by immunohistochemical (IHC) staining of tissue microarrays (TMA) comprising of tumors from 103 patients with stage III and IV metastatic melanoma." (PMID 25940796, 2015). "As the secreted form of PAPPA has been implicated in the progression of some types of cancer, we next determined the secreted PAPPA levels in conditioned media by solid-phase ELISA in a subset of the high and low PAPPA expressing melanoma cell lines." (PMID 25940796, 2015). "Indirect and specific inhibition of IGF-IR signalling by inhibition of PAPPA, alone or in combination with current treatments represents a promising approach which merits further evaluation as a new therapeutic target for melanoma." (PMID 25940796, 2015). "Here we examine the functional role of PAPPA during melanoma progression and demonstrate that PAPPA activity modifies melanoma migration and invasiveness." (PMID 25940796, 2015). "We examined PAPPA mRNA expression by quantitative real-time RT-PCR (qRT-PCR) in a panel of human melanoma cell lines that were derived from resected melanoma metastases and found it to be variably expressed." (PMID 25940796, 2015). "In conclusion, our study provides strong evidence for an important role of PAPPA in melanoma progression." (PMID 25940796, 2015). "IGFBPs, the putative targets of proteolytic action of PAPPA were differentially expressed between mesenchymal-like and epithelial-like melanoma cells." (PMID 25940796, 2015). "We show that PAPPA is widely expressed by metastatic melanoma tumors and is elevated in melanoma cells exhibiting mesenchymal, invasive and label-retaining phenotypes." (PMID 25940796, 2015). "Taken together, these findings indicate that PAPPA can enhance melanoma cell migration by inducing IGF-mediated EMT." (PMID 25940796, 2015). "We suppressed expression and secretion of PAPPA with two different siRNAs in two melanoma cell lines expressing high PAPPA levels, LM-MEL-12 and LM-MEL-44." (PMID 25940796, 2015). "This points to a probable role for PAPPA in accelerating the progression of melanoma that is observed in pregnancy." (PMID 25940796, 2015). "Here, we clearly demonstrate that sera derived from pregnant women increases melanoma cell migration, an effect which is effectively attenuated by neutralising PAPPA." (PMID 25940796, 2015). "We found that PAPPA is highly expressed and secreted by melanoma cells with a mesenchymal phenotype and our data suggests a role in melanoma promotion." (PMID 25940796, 2015). "Melanoma cells co-incubated with an anti-PAPPA antibody showed significant decrease in the migratory ability." (PMID 25940796, 2015). "This demonstrates the association between the PAPPA/IGF axis and a mesenchymal phenotype in melanoma." (PMID 25940796, 2015). "Overall, these results imply a prominent role for PAPPA in melanoma invasion in vitro and in vivo." (PMID 25940796, 2015).